MRPL15 (mitochondrial ribosomal protein L15)
Diseases named in the same sentence as MRPL15 in open-access papers (continued):
Sharing a sentence is not in itself a finding about the gene and the disease.
endometrial cancer (1 paper, 2026). Primary or metastatic malignant neoplasm involving the endometrium (mucous membrane that lines the endometrial cavity). "Additionally, three genes—MRPL15, MTFR2, and MTHFD2—were found functionally linked to MRS2, and their upregulation is associated with unfavorable outcomes in endometrial cancer patients." (PMID 41551444, 2026).
large cell lung carcinoma (1 paper, 2021). "Meanwhile, MRPL15 ranked within the top 5% up-regulated genes in large cell lung carcinoma based on mRNA expression in Oncomine database." (PMID 34026630, 2021).
ovarian benign tumors (1 paper, 2021). "Furthermore, the expression of MRPL15 in ovarian borderline tumors was significantly higher than in ovarian benign tumors (p = 0.0035) and normal ovarian tissues (p = 0.0012)." (PMID 33934540, 2021).
ovarian serous carcinoma (1 paper, 2021). "Analysis of the Oncomine database showed that the copy number of MRPL15 in ovarian serous carcinoma is significantly higher than that in normal ovarian and blood samples." (PMID 33934540, 2021).
ovarian tumours (1 paper, 2024). "MRPL15 was consistently highly expressed in ovarian tumours compared to normal tissue; significantly associated with late stage disease, and was associated with poor survival when compared to patients with low MRPL15 expression." (PMID 39354291, 2024).
schizophrenia (1 paper, 2021). A major psychotic disorder characterized by abnormalities in the perception or expression of reality. "MRPL15 may also be related to the closure or disorder of the biological function of mitochondria and in the function of energy metabolism in schizophrenia." (PMID 34016794, 2021).
serous ovarian cancer (1 paper, 2021). "The results indicate that high expression of MRPL15 leads to poor OS in patients with advanced serous ovarian cancer (p = 0.033)." (PMID 33934540, 2021).
cancer (7 papers, 2006 to 2025). A tumor composed of atypical neoplastic, often pleomorphic cells that invade other tissues. "MRPL15 is a mitochondrial ribosomal protein that plays a role in protein synthesis within the mitochondria which has been identified as a biomarker for cancers." (PMID 37289743, 2023). "In our work, higher expression of MRPL15 was observed in pan-cancers tissues than adjacent normal tissues using online database, including LUAD and LUSC." (PMID 34026630, 2021). "Actually, HCK overexpression has also been observed in NSCLC and HCK activation has been reported to force the recruitment of immune cells into tumors in many cancers, which was consistent with the phenotype of up-regulated MRPL15 in our present study." (PMID 34026630, 2021). "IHC staining of MRPL15 was performed in 118 cases of epithelial ovarian tissues, including 81 cases of malignant tumor tissues, 15 cases of borderline tumor tissues, 12 cases of benign tumor tissues, and 10 normal tissues." (PMID 33934540, 2021). "The analysis revealed that MRPL15 was up-regulated in pan-cancer." (PMID 34026630, 2021). "However, studies are needed to confirm that hypomethylation of MRPL15 is related to the occurrence or development of cancer." (PMID 33934540, 2021). "Genes encoding components of the translation machinery, the mitochondrial ribosomal protein MRPL15 and cytosolic ribosomal proteins RPL7 and RPS20, are located in this region, highlighting the need for enhanced translation in cancer cells." (PMID 16982006, 2006). "KEGG enrichment analysis of the top 150 mutant genes in the high‐MRPL15‐expression group showed that these genes are mainly involved in protein digestion and absorption, PI3 K/Akt signaling pathway, miRNA in cancer, extracellular matrix–receptor interaction, and other pathways." (PMID 33934540, 2021).
tumor (6 papers, 2021 to 2025). "Studies have shown that inhibiting the expression of MRPL15 can re-sensitize tumor cells to the drug." (PMID 40371222, 2025). "Regarding the correlation of T cell proliferation-related genes with MSI, MRPL15 was positively correlated with 14 tumors, while negatively correlated with one tumor." (PMID 39068665, 2024). "Here, we first declared that MRPL15 was up-regulated in tumor tissues in patients with NSCLC via multiple cohorts including GEPIA, ONCOMINE and eight GEO series (GSE8569, GSE101929, GSE33532, GSE27262, GSE21933, GSE19804, GSE19188, GSE18842)." (PMID 34026630, 2021). "We initially examined the level of MRPL15 expression in multiple tumor tissues in GEPIA." (PMID 34026630, 2021). "The expression of MRPL15 in LUAD or LUSC was obviously higher than in non-tumor tissues." (PMID 34026630, 2021). "Similarly, MRPL15 expression in NSCLC is negatively correlated with immune infiltration, including immune and stromal scores and tumor-infiltrating lymphocytes (TILs)." (PMID 40371222, 2025). "The specific staining was observed mainly in the cytoplasm and the expression scores of MRPL15 were significantly higher in tumor tissues than in adjacent non-tumorous tissues." (PMID 34026630, 2021).
MRPL15 also shares sentences with these, for which no sentence is quoted: benign tumor (1 paper); epithelial benign tumor (1); gastric cancer (1); hepatocellular carcinoma (1); ovarian endometrioid carcinoma (1); ovarian serous cystadenocarcinoma (1).